ABCA3 (ATP binding cassette subfamily A member 3)
Diseases named in the same sentence as ABCA3 in open-access papers (continued):
Sharing a sentence is not in itself a finding about the gene and the disease.
interstitial lung disease (continued). "Pathogenic variants in the genes that encode SP-B and SP-C (SFTPB and SFTPC) and genes that are involved in surfactant production (ABCA3 and NKX2-1) result in surfactant dysfunction disorders, one of the genetic causes of interstitial lung disease (ILD) (10, 19, –21)." (PMID 35121658, 2022). "ABCA3 mutations are usually associated with life-threatening neonatal respiratory distress syndrome (NRDS) in full-term babies, and some rare patients develop interstitial lung disease (ILD) during childhood or adulthood." (PMID 34638622, 2021). "The mutations in the ABCA3 (ATP-binding cassette transporter subfamily A member 3) gene could result in lethal respiratory distress syndrome (RDS) in neonates and interstitial lung disease (ILD) in infants and children." (PMID 32363169, 2020). "This provides a proof of principle and a first step for the development of pharmacological therapies for interstitial lung diseases caused by ABCA3 mutations, for which currently no treatment is available." (PMID 31210424, 2019). "Mutations in ABCA3 display a common genetic cause for diseases caused by surfactant deficiency like respiratory distress in neonates and interstitial lung disease in children and adults, for which currently no causal therapy exists." (PMID 31210424, 2019). "In contrast, another study proposes that having heterozygous R288K variants in ABCA3 alone may not be sufficient to trigger interstitial lung disease in the absence of additional contributing factors." (PMID 38203821, 2024). "For example, decreased expression of ABCA3 or SP-B results in more severe, neonatal onset disease, whereas alterations in SP-C expression result in interstitial lung disease (ILD) in older individuals." (PMID 33799761, 2021). "The results of a recent randomized controlled phase 2 trial of HCQ in 35 patients with various forms of interstitial lung disease (caused by the pathogenic variants of SFTPC, ABCA3, NKX2.1, TBX4, COPA, etc.)did not identify an overall HCQ treatment effect." (PMID 41181172, 2025).
respiratory distress syndrome (18 papers, 2011 to 2025). "We report a late preterm Bosnian baby boy (36 weeks) who suffered from a severe form of respiratory distress syndrome with poor response to intensive conventional management and whole exome sequencing revealed homozygous ABCA3 mis-sense mutation." (PMID 33526094, 2021). "An autosomal recessive pattern of ABCA3 deficiency has been described in neonatal respiratory distress syndrome and was recently extended to fibrotic lung disease in middle-aged and elderly population." (PMID 28642621, 2017). "Mutations in ABCA3 cause an often fatal severe respiratory distress syndrome in new-borns and diffuse parenchymal lung disease in children (chILD)." (PMID 27031696, 2016). "Although considerable progress has been made in understanding the role of ABCA3 in pulmonary surfactant deficiencies, phospholipid homeostasis, and respiratory distress syndromes, many experimental issues have still to be solved." (PMID 26295388, 2015). "Bi-allelic loss-of-function mutations of SFTPB, the gene encoding surfactant protein-B (SP-B) and ABCA3, which encodes ATP-binding cassette transporter A3 (ABCA3) typically present as lethal respiratory distress syndrome in neonates." (PMID 21867529, 2011). "Neonatal respiratory distress syndrome may result from variants in the ABCA3 gene or genes encoding surfactant proteins (SFTPA, SFTPB, SFTPC, SFTPD)." (PMID 38541145, 2024). "Mutations in the gene coding for the triphosphate binding cassette transporter A3 (ABCA3), which facilitates the transfer of lipids to lamellar bodies, constitute the most frequent genetic cause of severe neonatal respiratory distress syndrome and chronic interstitial lung disease in children." (PMID 33526094, 2021). "Dysfunctional ABCA3 disrupts lamellar body phospholipid export, causing respiratory distress syndrome (RDS), and pediatric and adult interstitial lung disease, which is a family of related conditions characterised by inflammation and fibrosis of the pulmonary interstitium." (PMID 28241820, 2017). "ECI1 and ABCA3 would only be expected to cause disease in an autosomal recessive fashion, likely explaining the lack of any history of neonatal respiratory distress syndrome and/or metabolic disease." (PMID 23936691, 2013). "Indeed, mutations in the human Abca3 gene are associated with lethal respiratory distress syndrome in human newborns who die at birth because they do not contain adequate amounts of surfactant material." (PMID 38970705, 2024).
respiratory failure (17 papers, 2005 to 2025). The significant impairment of gas exchange within the lungs resulting in hypoxia, hypercarbia, or both, to the extent that organ tissue perfusion is severely compromised. "Among these, mutations in the ABCA3 gene disrupt surfactant metabolism and can lead to severe, treatment-refractory respiratory failure." (PMID 40852890, 2025). "Abca3 inactivation in mice results in respiratory failure, surfactant loss, depletion of lung phosphatidylglycerol and impaired LB formation." (PMID 41148307, 2025). "Mutations in the Abca3, Sp-b, and Sp-c genes are associated with congenital respiratory disorders in infants, children, and adults, leading to respiratory failure." (PMID 41148307, 2025). "Consistently, mutations in the homeodomain–containing transcription factor TTF–1, master regulator of surfactant protein and ABCA3 expression, were also associated with respiratory failure." (PMID 32493486, 2020). "We demonstrate a case of a one-term newborn male with lethal respiratory failure caused by homozygous missense ABCA3 gene mutation c.3445G>A (p.Asp1149Asn), which, to our knowledge, was not previously reported as a causative agent of newborn lethal RDS." (PMID 31331098, 2019). "Over 100 ABCA3 mutations have been identified in neonates with respiratory failure and in older children with ILD." (PMID 20727133, 2010). "Recessive mutations in the ABCA3 gene were first attributed to fatal respiratory failure in term neonates but are increasingly being recognized as a cause of ILD in older children and young adults." (PMID 20727133, 2010). "Outcome in patients with ABCA3 mutations is variable ranging from severe irreversible respiratory failure in early infancy to chronic interstitial lung disease in childhood (ChILD) usually with the need for lung transplantation in many patients surviving this rare disorder." (PMID 33526094, 2021). "Recessive frameshift or nonsense ABCA3 mutations are associated with respiratory failure and neonatal death but milder phenotypes of ABCA3 deficiency due to missense, splice site, and insertion/deletions may result in survival beyond infancy." (PMID 32782805, 2020). "Deficiency of ABCA3 also recapitulates this phenotype and causes respiratory failure." (PMID 32493486, 2020). "In animal experiments, a mouse model of the deletion of ABCA3 exons 4–7 showed the mechanism of the ABCA3 deletion leading to respiratory failure in mice." (PMID 34715861, 2021). "Pathogenic variants in this gene give rise to a rare form of progressive respiratory failure, which is linked to changes in surfactant production, structure, and balance, influencing the expression of associated genes, including SFTPB, SFTPC, and ABCA3." (PMID 38203821, 2024). "In addition, the ABCA3 gene has also been identified to contribute to neonatal recurrent pulmonary hypertension and respiratory failure." (PMID 36620618, 2022). "ABCA3 mutations were associated with fatal respiratory failure in neonates without SP-B or SP-C deficiency and with non-fatal ILD in one older child." (PMID 15819986, 2005). "Epitope mimicry analysis revealed that respiratory failure in population with some MHC polymorphisms was due to the high similarity between envelope and surface glycoproteins and two human proteins important for the prevention of alveolar collapse and respiratory failure, NKX2-1 and ABCA3 proteins." (PMID 36897962, 2023).
pulmonary fibrosis (12 papers, 2014 to 2025). Chronic progressive interstitial lung disorder characterized by the replacement of the lung tissue by connective tissue, leading to progressive dyspnea, respiratory failure, or right heart failure. "ABCA3 is a phospholipid transporter associated with pulmonary surfactant homeostasis, and mutations in the ABCA3 gene cause pulmonary fibrosis in children and adults." (PMID 36211517, 2022). "This resulted in the exclusion of well-defined monogenic pulmonary fibrosis genes, such as ABCA3 or NOP10, which show recessive inheritance." (PMID 40311650, 2025). "We tested the level of fatty acid metabolism and the predictive value of Abca3 and Cyp24a1 in rat models with different degrees of pulmonary fibrosis to verify the accuracy of the prediction results." (PMID 36211517, 2022). "The variants involved two genes associated with surfactant metabolism dysfunction (ABCA3 and CSF2RB), two with pulmonary fibrosis (MUC5B and SFTP), one with bronchiectasis (SCNN1B), and one with alpha-1-antitrypsin deficiency (SERPINA1)." (PMID 33526882, 2021). "The results showed that in AT-II-associated proteins (LAMP3, ABCA3, and SFTPC), the expression of ABCA3 and SFTPC was significantly downregulated, which can also suggest the loss of AT II in pulmonary fibrosis." (PMID 34645797, 2021). "We suggest that ABCA3 gene should be considered in genetic testing in the occurrence of familial pulmonary fibrosis." (PMID 24730976, 2014). "This is the case of MUC5B rs35705950 mutation, ABCA3 mutation and the mutation in surfactant proteins, which were associated in our study with a predominant atypical pattern of pulmonary fibrosis, but not the classical UIP pattern at the time of diagnosis." (PMID 33922858, 2021). "A search for this ABCA3 mutation resulted negative in 195 Italian healthy individuals, in 30 Italian patients with autoimmune pulmonary alveolar proteinosis, and 113 patients with idiopathic pulmonary fibrosis (data not shown)." (PMID 24730976, 2014). "Although there is currently no data on the participation of ABCA3 in the pathogenesis of COPD, it is known that mutations in the ABCA3 gene can lead to lung fibrosis and the development of emphysema." (PMID 34201488, 2021). "However, whether variations in ABCA3 have a role in the development of adult ILD, including idiopathic pulmonary fibrosis (IPF), remains to be addressed." (PMID 28642621, 2017).
breast cancer (11 papers, 2004 to 2025). A primary or metastatic malignant neoplasm involving the breast. "The loss of ABCA3 protein expression was related to a more aggressive phenotype in breast cancer patients." (PMID 32977823, 2020). "The upregulation of ABCA3 was associated with a better prognosis of patients with breast cancer." (PMID 32977823, 2020). "In accordance with the findings above, our study also suggested that upregulated ABCA3 may be related to the good prognosis of breast cancer and served as a protective factor in breast cancer." (PMID 32977823, 2020). "Moreover, SALL4 is enriched in SP in breast cancer cell line MCF7 along with ABCA3 and ABCG2, and increased SALL4 expression led to an expansion of SP in MCF7 cells." (PMID 21526180, 2011). "These side population cells have been identified in breast cancer cell lines of luminal type, and these cells overexpress transporter genes ABCG2 (ATP-binding cassette, subfamily G, member 2) and ABCA3 (ATP-binding cassette, subfamily A, member 3)." (PMID 17062128, 2006). "ABCA3, CCL22, FOXJ1, IL1RN, and MAP2K6 may serve as good prognostic factors, while KCNIP3 and MRPL13 may be poor prognostic factors for the prognosis of breast cancer." (PMID 32977823, 2020). "NRIP1, GREB1, and ABCA3 are all genes found to be ER responsive in at least two cell lines; they have a discernable ERE around the TSS, blocked by ICI and not inhibited by CHX, and their expression can discern ER status in breast cancers." (PMID 15345050, 2004). "Biomarkers including FOXJ1, CCL22, ABCA3 and IL1RN may be good prognostic factors in breast cancer." (PMID 36397112, 2022). "Among the delivered proteins are frequently described ATP-binding cassette (ABC) family, like P-glycoprotein (P-gp, MDR1, and ABCB1), breast cancer (BC)-resistant proteins (ABCG2, BRCP, and ABCA3), and multidrug-resistant protein 1 (MRP-1)." (PMID 36091133, 2022). "In conclusion, ABCA3, CCL22, FOXJ1, MAP2K6, and IL1RN may serve as good prognostic factors, while KCNIP3 and MRPL13 may be poor prognostic biomarkers to predict the recurrence and prognosis of breast cancer." (PMID 32977823, 2020).
idiopathic pulmonary fibrosis (6 papers, 2014 to 2025). Idiopathic pulmonary fibrosis (IPF) is a nonneoplastic pulmonary disease that is characterized by the formation of scar tissue within the lungs in the absence of any known cause. "Sequence variants in genes for surfactant proteins (SFTPC, SFTPA1, SFTPA2, ABCA3), polymorphisms in MUC5B or TOLLIP, and mutations in telomere genes (TERT, TERC, PARN, and RTEL1) are associated with an increased risk of idiopathic pulmonary fibrosis (IPF)." (PMID 36864460, 2023). "Mutations in the ABCA3 gene are associated with surfactant dysfunction, familial lung diseases ranging from respiratory failure in newborns or interstitial lung disease in children to idiopathic pulmonary fibrosis (IPF) or diffuse parenchymal lung disease in adults." (PMID 35011607, 2021).
cystic fibrosis (5 papers, 2005 to 2024). Autosomal recessive disorder caused by pathogenic variants in the CFTR gene (cystic fibrosis transmembrane conductance regulator), which encodes a chloride and bicarbonate channel expressed in epithelial cells, and follow the diagnosis criteria. "Various vectors, compounds that can improve cellular ABCA3 trafficking or function (similar to those used in cystic fibrosis), and gene editing strategies are also under study." (PMID 39457702, 2024). "Mutations in the cystic fibrosis transmembrane conductance regulator (CFTR) gene can cause cystic fibrosis, and mutations in ABCA1 and ABCA3 are responsible for respectively Tangier disease and fatal surfactant deficiency." (PMID 15967026, 2005). "Encouragingly, based on similarities between CFTR (ABCC7) — itself an ABC transporter protein and the causal gene for cystic fibrosis — and ABCA3, recent studies have repurposed drugs developed to modulate CFTR function for restoration of ABCA3 function in cancer cell line models." (PMID 38226623, 2024).
acute myeloid leukemia (4 papers, 2020 to 2023). Acute myeloid leukemia (AML) is a group of neoplasms arising from precursor cells committed to the myeloid cell-line differentiation. "ABCA3 is involved in phospholipid transport for surfactant production in lung tissue and is overexpressed in childhood acute myeloid leukemia." (PMID 37242805, 2023). "The increased expression of ABCA3 appears to be associated with a resistant phenotype only in acute myeloid leukaemia (AML) patients but not in CML patients." (PMID 36899844, 2023). "In addition, sensitivity to rituximab was inhibited by EEV delivery of ATP-binding cassette (ABC) transporter A3 (ABCA3), which mediated subcellular drug sequestration in acute myeloid leukemia (AML)." (PMID 33126572, 2020).
lung carcinoma (4 papers, 2014 to 2025). "Several ABC transporters are linked to lung cancer, such as ABCC1, ABCC3, ABCA3 and ABCC5." (PMID 24625834, 2014). "However, while lung cancer was identified in Case 1, noting a significant smoking history, there is no known association between ABCA3 pathogenic variant‐related ILD and lung cancer." (PMID 40746635, 2025).
chronic lung disease (3 papers, 2012 to 2024). According to the definitions of the American and British Thoracic Societies, including pulmonary functional tests, X-rays, and CT scans for items such as fibrosis, bronchiectasis, bullae, emphysema, nodular or lymphomatous abnormalities. "A relatively common mutation in ABCA3, E292V, is associated with partially impaired ABCA3 function and with milder chronic lung disease in childhood." (PMID 22866751, 2012). "This is an important finding as 1.3% in the Danish general population has partially reduced ABCA3 function due to E292V and since this variant has been linked previously with severe chronic lung disease in E292V heterozygotes and compound heterozygotes." (PMID 22866751, 2012). "Furthermore, the study reported a notable association of ABCA3 rs13332514 (c.1059G>A) with chronic lung disease." (PMID 38541145, 2024). "This is an important finding as 1.3% in the Danish general population has partially reduced ABCA3 function due to E292V, and since this variant has been linked previously with severe chronic lung disease in heterozygous and compound heterozygous E292V carriers." (PMID 22866751, 2012). "Mutations in ATP-binding-cassette-member A3 (ABCA3) are related to severe chronic lung disease in neonates and children, but frequency of chronic lung disease due to ABCA3 mutations in the general population is unknown." (PMID 22866751, 2012). "For instance, mutations of the surfactant protein (SP)-A and -C, or ATP binding cassette subfamily A member 3 (ABCA3) represent well-described examples of alveolar epithelial type 2 distress resulting in chronic lung disease and fibrosis." (PMID 33282895, 2020).
emphysema (3 papers, 2012 to 2021). "Because mice with 50% reduced ABCA3 die from respiratory distress or develop emphysema, individuals heterozygous for ABCA3 variants may also be at increased risk of emphysema/COPD." (PMID 22866751, 2012). "Most mice with Abca3 deletion in respiratory epithelial cells die shortly after birth from respiratory distress caused by surfactant deficiency, and emphysema was being developed in the absence of signs of severe pulmonary inflammation in the surviving mice." (PMID 34201488, 2021).
leukemia (3 papers, 2012 to 2021). A malignant (clonal) hematologic disorder, involving hematopoietic stem cells and characterized by the presence of primitive or atypical myeloid or lymphoid cells in the bone marrow and the blood. "Moreover, the expression level of ABCA3 lost the correlation with SALL4 expression in leukemia patients." (PMID 23067006, 2012).
lymphoma (3 papers, 2013 to 2022). A malignant (clonal) proliferation of B- lymphocytes or T- lymphocytes which involves the lymph nodes, bone marrow and/or extranodal sites. "Concordantly, silencing ABCA3 also increased the susceptibility of lymphoma cells to immunochemotherapy." (PMID 26082317, 2013). "Pharmacological blocking and/or silencing of ABCA3 inhibits exosome release, thereby enhancing the sensitivity of lymphoma cells to rituximab." (PMID 35692747, 2022). "Treatment of lymphoma cells with the indomethacin can reduce expression levels of ABCA3, which is important for exosome biosynthesis, and thus inhibiting exosomes biogenesis." (PMID 35692747, 2022). "Lymphoma derived exosomes were analysed by HPLC measurement and ABC transporter A3 (ABCA3) expression." (PMID 26082317, 2013).
acute lymphoblastic leukemia (2 papers, 2024). Leukemia with an acute onset, characterized by the presence of lymphoblasts in the bone marrow and the peripheral blood. "NEAT1 can target up-regulate the expression of ABCA3 through sponge miR-335-3p, and ultimately lead to chemotherapy resistance in children with acute lymphoblastic leukemia." (PMID 38970092, 2024). "ABCA3 is a member of the ABC1 subfamily and is up-regulated in the multidrug-resistant group of childhood acute lymphoblastic leukemia." (PMID 38970092, 2024).